TNF (tumor necrosis factor)
Diseases named in the same sentence as TNF in open-access papers (continued):
Sharing a sentence is not in itself a finding about the gene and the disease.
tumor (continued). "In the 3-methylcholanthrene induced tumor mouse model, a gold‐manganese oxide nanocomposite induced hypoxia in the tumor microenvironment, and the level of pro-inflammatory cytokines: TNF-α, IL-10, and HIF-1α were decreased." (PMID 38082190, 2024). "Research into how BCAR3 expression is controlled within the tumor microenvironment, where inflammatory cytokines such as IL-1 and TNF are prevalent, is particularly vital." (PMID 38730626, 2024). "This system involved in transforming the bacteria with plasmids expressing TNF-α and decorating them with biomineralized gold nanoparticles (AuNPs) to improve the effectiveness of tumor therapy." (PMID 38472176, 2024). "Reduced IL-10 levels can lead to the insufficient regulation of TNF-α and anti-tumour T cell responses, fostering tumor-promoting inflammation and contributing to cancer progression." (PMID 39684475, 2024). "TNF-α is a cytokine, secreted by macrophages, which facilitates cell death of certain tumor cell lines." (PMID 39897071, 2024). "PD-L1+ Bregs were found to inhibit proliferation of CD8+ T cells, CD4+ CD25- T cells and CD49b+ NK cells in a murine model, via reduced IFN-γ and TNF-α secretion, which ultimately promoted tumour growth in murine breast cancer models." (PMID 39346706, 2024). "Studies focusing on solid tumors, particularly breast cancer, nasopharyngeal carcinoma, and melanoma, have demonstrated a positive correlation between the production of TNF-α by peripheral γδT cells and their contribution to tumor defense." (PMID 38840908, 2024). "In early murine tumor stages, TANs were more cytotoxic, producing more TNF-α, whereas TANs developed a pro-tumorigenic phenotype in well-established tumors." (PMID 38572312, 2024). "Chemokines and cytokines in the tumor microenvironment exert a chemotactic effect on TAMs, including tumor necrosis factor-α and monocyte chemoattractant protein-1, among others." (PMID 39723376, 2024). "In chemically induced models of colitis and CRC, TNFα produced by mononuclear cells appears to play a pivotal role in inflammation and subsequent tumor development." (PMID 38799159, 2024). "The T cell receptor (TCR) on CD8+ T cells recognizes and binds to the tumor antigen-MHC-I complex on the cell surface, triggering the release of cytotoxic substances such as perforin, tumor necrosis factor, and interferon to kill tumor cells." (PMID 39329721, 2024). "EVs originating from tumor cells often contain pro-inflammatory cytokines and chemokines, including TNF-α, IL-6, and IL-1β." (PMID 38802952, 2024). "Primary and metastatic tumor cells can release tumor necrosis factor (TGF), Interleukin(IL)-8, and Neurotrophin-3 (NT-3) to recruit BMSCs to the tumor site." (PMID 38770000, 2024). "Type 1 immunity cytokines like IL-12 and TNF-α have been shown to initiate anti-tumor immune response exhibited by NK cells, CD8+ T cells and T helper 1 (Th1) cells." (PMID 39411143, 2024). "In this regard, it is suggested that prolonged inflammation contributes to tumor development and that proinflammatory cytokines play an important role with TNF-α as the possible molecular link between chronic inflammation and cancer." (PMID 39337365, 2024). "As an example, TNFα is involved in tumor promotion, aggressiveness, infiltration of tumor promoting macrophages, angiogenesis and IL-8 expression." (PMID 37979099, 2024). "In the case of TNF-α we observed significance difference in mRNA levels in men, patients over 60 years old with a tumor in both localizations, and in N0-N1, G1-G3 TNM stages." (PMID 38175424, 2024). "The mechanism of this direct cytotoxicity is however less established since T cells are known to use different approaches to induce tumor cell death such as cytokine release, tumor necrosis factor (TNF) trimerization, and exocytosis of cytotoxic enzymes." (PMID 38307835, 2024).
tumor (continued). "Clinical tumor progression and metastasis are affected by a complex environment that includes an accumulation of inflammatory cytokines such as IL1β and TNFα that, in turn, target the tumor cells." (PMID 39199704, 2024). "Typically, M1 macrophages are induced by LPS and IFN-γ, and they produce pro-inflammatory cytokines, including IL-6, TNF-α, and IL-1β, which possess potent anti-tumor effects." (PMID 39795180, 2024). "TAMs secrete various cytokines (such as IFN-γ, TNF) to upregulate the PD-L1 expression in tumor cells." (PMID 38762484, 2024). "Deep analysis of scRNA and bulk RNA sequencing data revealed the increased interactions between CXCR1+ neutrophils and tumor cells and activated TNF-α/NF-κB signaling pathway in tumor cells of resistant samples." (PMID 39638994, 2024). "Programmed death molecule ligand-1 (PD-L1) is an important immunosuppressive factor, which can convert TNF-α induced apoptosis of cancer cells into pyroptosis, leading to tumor necrosis." (PMID 38877579, 2024). "NF-κB regulates pro-inflammatory cytokines such as TNF-α, IL-1β, and IL-6, which contribute to tumor progression and metastasis." (PMID 39861671, 2024). "We describe that tumor necrosis factor (TNF) alpha released by patient-derived tumor exosomes contributes to the onset of brain tumor-related epilepsy (BTRE)." (PMID 39088270, 2024). "Given the cytotoxic impact of heightened TNF-α levels and massive T cell infiltration on tumor cells within a short timeframe, we employed neutralizing antibodies targeting TNF-α and CD8." (PMID 38296939, 2024). "IFNγ has been strongly associated with anti-tumor efficacy in preclinical and clinical studies;21 however, the role of TNFα in promoting tumor immunity is more ambiguous and most likely context dependent." (PMID 38333710, 2024). "Cancer cells can produce CCL2 and other chemokines in response to TNF stimulation, which enhances their metastatic potential and recruit leukocytes with pro-metastatic effects to the tumor microenvironment." (PMID 39206193, 2024). "Inhibiting TNFα reduces the anti-PD-1-induced cell death of tumor-infiltrating lymphocytes, thus amplifying the anticancer immune response." (PMID 38473748, 2024). "In this way, by blocking the NFκB signaling, which is an important factor for tumor progression in inflammation-related cancers, and by decreasing TNF-α and some inflammatory cytokines such as IL-6, tumor progression can be alleviated." (PMID 39267853, 2024). "In tumors, inflammatory chemokines and cytokines such as TNF regulate the activity of infiltrating immune cells, and the behavior of cancer cells influences tumor growth, dissemination, and response to therapy." (PMID 39201710, 2024). "Apart from CD8+ T cells, CD4+ T cells also cooperate with IFNγ signaling through TNFα-p55 axis to induce tumor dormancy in a pancreatic cancer mouse model." (PMID 38216787, 2024). "Characteristically, M1 macrophages release pro-inflammatory agents like TNF, IL-1, IL-6, and IL-12, which possess tumor-fighting properties." (PMID 39702158, 2024). "Investigators found that injecting Salmonella enterica Serovar Typhimurium intravenously resulted in a considerable rise in TNF-α concentrations in the blood in an ectopic tumor model." (PMID 39594765, 2024). "Contrastingly, the C57BL/6 mice showed a significant reduction in tumor volume in mice treated with the FAP CAR, and this also correlated with an increased number of host CD8+ T cells within the tumor and higher numbers of TNF-α-producing CD4+ T cells." (PMID 39335157, 2024). "In the XLLXF combined with trastuzumab groups, we observed increased expressions of JAK1 and TNF-α on lymphocytes in tumor tissues by IHC staining." (PMID 38379418, 2024). "Leveraging sustained melanin production, BMB181 exhibits a robust capacity to induce tumor cell death through photonic hyperthermia as well as inhibit inflammatory cytokines such as tumor necrosis factor‐α (TNF‐α) and interleukin 6 (IL‐6) release." (PMID 38943265, 2024).
tumor (continued). "M1-like TAMs enhance anti-tumor immunity by producing cytokines like IFN-γ and TNF-α, which activate T cells and other immune cells, and by efficiently presenting antigens to assist T cells in targeting and eliminating tumor cells." (PMID 38341519, 2024). "One of the major cytokines involved in this inflammation is IL-1β, which promotes tumor growth and invasiveness through the stimulation of IL-6, TGFβ, and TNFα." (PMID 39394174, 2024). "Investigation at molecular level unveiled the reduced TNF‐α level on systemic circulation, suppression of intracellular adhesion molecule‐1, and diminish leukocyte movement toward tumor mass." (PMID 39584048, 2024). "Here, we found that VDUP1 deficiency significantly increased the mRNA levels of IL-6 and TNF-α in the tumor tissues of AOM/DSS-treated mice compared to those in the tumor tissues of WT mice." (PMID 39272794, 2024). "Unlike other classic CD8+ T cells, which rely on the cytotoxic molecule Granzyme K (GZMK), CD8+ MAIT cells primarily exert their anti‐tumor effects through the non‐specific molecules, tumor necrosis factor (TNF)." (PMID 39716897, 2024). "Activation of M1 macrophages leads to the release of various anti-tumor cytokines and chemicals, including tumor necrosis factor-α (TNF-α), interferon-γ (IFN-γ), nitric oxide (NO), and interleukin-12 (IL-12), among others." (PMID 38910204, 2024). "Tumor necrosis factor (TNF) promotes tumor activity through various pathways, including cytokine cascade stimulation, fibrotic response induction, and the alteration of adhesion receptors." (PMID 38928150, 2024). "PD-L1 protein expression in tumor cells is upregulated by interleukin (IL)-1, IL-6, tumor necrosis factor-α (TNF-α), and interferon-γ (IFN-γ)." (PMID 38817669, 2024). "LPS-activated macrophages will secrete harmful substances that disintegrate tumor cells, including TNF, NO and ROS." (PMID 39175095, 2024). "Neutralizing TNF-α in tumor-bearing mice serum reduced blood input into tumors and delayed bacterial colonization." (PMID 39594765, 2024). "DCs, macrophages, and neutrophils exert their tumor cell-killing activity by releasing cytokines such as TNFα, IL-6, and IFNγ." (PMID 39204319, 2024). "Studies have shown that inflammatory cytokines such as TNF-α, IL-6, and IL-1β can activate cellular signaling pathways that promote tumor survival and growth." (PMID 39339213, 2024). "The in vivo studies have demonstrated that DHT effectively suppresses the growth of HeLa cells in xenograft tumor models, potentially through its regulation of TNF-α production." (PMID 38751791, 2024). "Prostaglandin E2 (PGE2) and TNF were the TME factors able to elicit the IL-1β+ TAM population with an inflammatory loop between tumor cells and IL-1β-expressing TAM, sustaining tumor growth." (PMID 38334625, 2024). "Reprogramming of neutrophils for the phenotypic switching to PMN‐MDSCs occurs due to G‐CSF, GM‐CSF, TGF‐β, TNF‐α, IFN‐γ, IFN‐β, and IL‐17 overexpressed by the tumor cells, cancer‐associated fibroblasts, and TAMs." (PMID 38703051, 2024). "Analysis of patient tumor data reveals that TGFβ, TNFα, and hypoxia signaling correlate with the mesenchymal subtype more than the proneural subtype." (PMID 38337036, 2024). "We conducted tumor treatment-related immune cell and Th1/Th2 subset detection in the patient, comparing the concentrations of 6 cytokines (IL-2, IL-4, IL-6, IL-10, TNF-α, and TNF-γ) and various immune cells in peripheral blood before and after treatment." (PMID 39871939, 2024). "TNF-α plays a role in inducing cell apoptosis, regulating the immune response of the body, regulating the vascular system of tumor tissue, and inducing programmed cell necrosis." (PMID 38994338, 2024). "Treatment with 5-FU and probiotics reduced the protein levels of anti-inflammatory IL-10 and noticeably increased the protein levels of proinflammatory IL-6 and TNF-α in tumor tissues." (PMID 39062024, 2024).
tumor (continued). "On the other hand, TNF-α is known to diminish tumor cell proliferation and initiate tumor regression, mainly by the induction of cancer cell death." (PMID 39411143, 2024). "As shown by the enrichment results, the two subclusters showed distinct expression patterns in tumor-associated pathways, including PI3K-Akt pathway, MAPK pathway, chemokine pathway, HIF-1 pathway, NF-κB pathway, and TNF pathway." (PMID 39507421, 2024). "MASL treatment upregulated TNF-α, Fas, and FasL expression levels, while suppressing anti-apoptotic NF-κB and mTOR pathways in tumor cells." (PMID 39683650, 2024). "Immune cells produce pro-inflammatory mediators such as TNF-α, IL-6, IL-1, IL-12, and iNOS, leading to reprogramming the immunosuppressive tumor microenvironment into an immunogenic one to aid in the elimination of tumors." (PMID 38974834, 2024). "M1-like TAMs secrete pro-inflammatory cytokines such as IL-1, IL-6, IL-12, and TNF-α, along with reactive oxygen species and nitrogen, which are essential for host defense and tumour cell death." (PMID 38475858, 2024). "Antibody-based delivery of TNFα to the tumor also increased the therapeutic efficacy of cancer vaccines by promoting T-cell infiltration." (PMID 38195677, 2024). "Combination therapy with MRTX849 resulted in a further reduction of intra-tumor M2-macrophages, exhibiting a stronger M1-macrophage phenotype with highest levels of TNF-α." (PMID 38191673, 2024). "The combination of calycosin and formononetin decreased the expression of NOS2 in tumor tissues and cells and decreased TNF‐α production in the tumor area." (PMID 38230908, 2024). "Specifically, TANs recruit B cells to a tumor site through TNFα and are responsible for subsequent differentiation into CD138+ IgG-producing plasma cells." (PMID 38572312, 2024). "It is therefore possible that the promotion of tumor cell adhesion of mesothelial cells by IL‐17A+TNF is partly mediated by an enhanced interaction of CD44 with hyaluronan." (PMID 38566518, 2024). "Recent studies on murine models have underscored that TNFα itself is produced by tumor cells, inducing increased production of growth factors, stimulation of angiogenesis, and enhanced capillary permeability." (PMID 38610706, 2024). "In response, T-cells secrete increased tumor necrosis factor-α (TNFα) and decreased interferon-γ (IFNγ), ultimately leading to decreased cytotoxicity and an increase in tumor growth." (PMID 38254784, 2024). "Our data indicate that CAR-modified macrophages exhibit marked NF-κB activation after engulfing tumor cells, leading to significant upregulation of the proinflammatory cytokines IL-1 and TNF-α." (PMID 39379603, 2024). "Tumors exhibiting cGAS positivity are characterized by elevated concentrations of T-cell-derived effector cytokines, such as IFN-γ and TNF-α, and demonstrate enhanced responsiveness to ICIs, indicative of a “hot” tumor phenotype." (PMID 38817608, 2024). "TNF, mainly produced by activated monocytes/macrophages 17, can kill and inhibit tumor cells 18 and promote the phagocytosis." (PMID 39440053, 2024). "In an animal model of anal sarcoma, the researchers used APS instead of TNF-α to induce maturation of bone marrow-derived DCs, which were then sensitized with the S180 tumor antigen, thereby obtaining a DC tumor vaccine." (PMID 38794206, 2024). "The results demonstrated that lymphocytes cultured with oncogenes-transfected tumor cells promoted an increase in the release of the cytokines IL-2, IL-4, IL-10, and TNF-α, with differences in the releases from different transfected oncoproteins." (PMID 39599846, 2024). "High levels of TNF-α lead to tumor cell necrosis and apoptosis, contributing to immune cytotoxicity and release of other inflammatory cytokines." (PMID 39635522, 2024). "Significant inhibition of tumor growth was observed, along with differences in the levels of measured cytokines such as IL-2, TNF-α, IFN-γ, and IL-4." (PMID 39367471, 2024).
tumor (continued). "TRADD, a downstream factor of TNF-α, mediates TNF-α-induced cell survival pathways in tumor and nerve cells." (PMID 39062455, 2024). "For example, through transcriptional upregulation of TAZ and its gene CYR61, which are pivotal for self-renewal and tumor initiation, TNF-α facilitated the expansion of both BCSCs-CD44+ and BCSCs-CD24+." (PMID 39609700, 2024). "Activated CD8+ T cells migrate to the tumor region to release cytotoxic molecules such as IFNγ, TNFα, perforin, and granzyme B, which activate anti-tumor immune responses and induce apoptosis in tumor cells." (PMID 39776907, 2024). "In fact, TNF has been recognized as a key regulator at all stages of tumor malignancies, including tumorigenesis, cancer cell proliferation, survival, angiogenesis, cellular invasion, and metastasis." (PMID 38337668, 2024). "Th17 cells express the cytokines IL-17, IL-21, IL-22 and other cytokines such as IFNγ and TNFα in human tumor tissues." (PMID 38833034, 2024). "Among them, TNF‐α and IL‐2 are produced by Th1 cells and mediate anti‐tumour effects, while Th2 cells produce IL‐6 and IL‐10 and promote tumour growth by suppressing the immune system." (PMID 38451046, 2024). "Different studies have demonstrated that while TNF and its superfamily members were crucial for hematopoiesis, prevention of bacterial infection, immune surveillance, and tumor regression; their dysregulation also contributed to various diseases." (PMID 38835752, 2024). "Tumor necrosis factor α (TNF-α) is one of the most significant promoter to cause basement membrane remodeling, paving the way for tumor invasion by decreasing COL4." (PMID 38546906, 2024). "Cytokines (IFN-γ, granzyme B, perforin, and TNF-α) secreted by T cells are important for maintaining immunosurveillance, and inhibition of these cytokines can promote the growth and metastasis of tumor cells." (PMID 38340166, 2024). "TNF-α is a pro-inflammatory cytokine that helps initiate and propagate the inflammatory response and cancers; it also has anti-tumor effects through apoptosis or necrosis." (PMID 38543544, 2024). "In this study, we identified a different regulatory way by which SPP1 + Macs released the cytokines TNF-α and IL-1β to promote tumor progression." (PMID 39726047, 2024). "Higher levels of TNF-α have been reported not only in subjects suffering from T2DM but also in the tumour microenvironment of BC patients, in which it covers an essential role in malignancy progression and metastasis." (PMID 39408212, 2024). "The B cell-activating factor (BAFF) belongs to the tumor necrosis factor and was found to be involved in tumor cell proliferation, survival and invasion." (PMID 39256468, 2024). "The next step of tumorigenesis is the proliferation and growth of tumor cells which is mainly induced by various cytokines(e.g.IL-1, IL-6, TNF-α), which is concluded in the process of promotion." (PMID 39493763, 2024). "High levels of pro-inflammatory cytokines such as IL-6 and TNF-α can promote tumor growth and metastasis." (PMID 39273009, 2024). "M1 macrophages, activated by IFN-γ and LPS, promote pro-inflammatory responses, secrete cytokines like TNF-α and IL-12, and are involved in pathogen phagocytosis and tumor cell elimination." (PMID 39769334, 2024). "TNF alters the charge of tumor cell membranes, making them more sensitive to Defensin, which in turn induces cell death and tumor regression." (PMID 39404408, 2024). "The activation of TNF-NFKB axis has already been revealed in several tumor types including the GBM21,26, while here, through a systematic analysis, we unraveled its association to spatial intratumoral heterogeneity, with consistency in several patient samples." (PMID 38562886, 2024). "This is in addition to the common idea that membrane-bound TNFR2 generates strong signals when it interacts with Mb-TNF-α, thereby activating various biological processes that support tumor growth." (PMID 39609700, 2024).